ENSG00000200536
Synonyms: LOC124900436
Gene: Small nucleolar RNA gene on chromosome 1 (110,272,484 to 110,272,607, forward strand). Ensembl gene ENSG00000200536.
Gene Ontology:
Biological process: RNA processing
Cellular component: nucleolus
Homologues: Paralogues in human: SNORA25B (77% identical), SNORA25 (77% identical).